MRC1 (mannose receptor C-type 1)
Diseases named in the same sentence as MRC1 in open-access papers (continued):
Sharing a sentence is not in itself a finding about the gene and the disease.
tumor (continued). "Additional correlation analyses showed that IL7R expression was significantly associated with markers of cells involved in immunosuppression such as CD68, CD163, MRC1, and IL10 (tumor‐associated macrophages), CD4, FOXP3 (regulator T lymphocytes) and CD274 (PD‐L1)." (PMID 36054746, 2022). "In addition, a subset of M2-like TAMs (MRC1+TIE2HiCXCR4Hi) were identified to accumulate around tumor vasculature in breast and lung tumors after chemotherapy, which contributed to tumor relapse after therapy." (PMID 34202979, 2021). "In addition to the reduction in M2 associated gene expression (Adm, Arg, Mrc1, F13a1) in TAMs, this study observed multiple therapeutic effects from BLZ945 treatment, such as reduced tumor aggressiveness and increased animal survival." (PMID 34988021, 2021). "MRC1 also participates in immune organization, for example by trafficking lymphocytes along lymphatic endothelium to draining lymph nodes, a process also exploited by tumours to metastasize to nodes." (PMID 31696318, 2020). "A surprising observation from our microscopy-based analysis of TAMs in a spontaneous murine breast tumor model, was that Arg1-expressing TAMs were almost exclusively located within ischemic tumor regions, while Mrc1-expressing TAMs were found in perivascular and other well-nurtured tumor regions." (PMID 29991530, 2018). "Additionally, the number of CD80- and mannose receptor C type 1 (MRC1)-expressing cells was decreased upon LPS administration in the tumor of the xenograft tumor." (PMID 29690614, 2018). "M2 type, expressing CD163 and MRC1, promoted tumor growth, invasion, angiogenesis, and metastasis." (PMID 28549420, 2017). "In addition, CMA1 and MRC1 were upregulated in patient normal mucosa compared to both healthy and tumor tissue." (PMID 29176937, 2017). "Three days after intracerebral injection of mannosylated clodronate liposomes in the metastatic brain, a decrease in MRC1 expression around the tumor foci was observed, which was statistically significant (unpaired t-test p < 0.05) compared to control liposome injected mice (n = 4 per group)." (PMID 29164051, 2017). "Compared with C-MOs, MAMPCs expressed higher levels of TAM signature genes (i.e., Arg1, Cdh1, Hmox1, Il1r2, Mrc1, and Stab1) that were also highly expressed by MAMs, suggesting that differentiation of C-MOs to MAMPCs (M-MDSCs) is directed toward the tumor-promoting macrophages." (PMID 29387063, 2017). "To further explore the role of ARF−/− macrophages on the modulation of angiogenesis, we isolated TAMs from B16F10 tumor xenografts and examined gene expression of some of the genes involved in M2 polarization (e.g. Ym-1 and MRC1) as well as in the angiogenic response." (PMID 27572316, 2016). "Intriguingly, classical M2 markers including Cd206 (Mrc1), Cd163, Pdl2 (Pdcd1lg2), Ccr3, Arg1 and many others were all markedly downregulated in TAMs isolated from the St2−/− background as compared with those isolated from tumours grown in wt mice." (PMID 27150562, 2016). "We therefore examined the expression of MRC1 in Huh7 orthotopic tumors and non-tumor mouse liver." (PMID 23724146, 2013). "The expression of mouse Mrc1 was detectable in non-tumor liver and in the Huh7 tumors." (PMID 23724146, 2013). "Tumor tissue samples, which lack alveoli, showed little MRC1 staining." (PMID 22509397, 2012). "Furthermore, engaging MRC1 via synthetic mimics of amphipathic host-defense peptides induces endocytosis, phagosome/lysosome formation, and autophagy, reprogramming M2-like TAMs to anti-tumor M1-like state." (PMID 38545103, 2024). "Furthermore, we found that SIRPA (the “don't eat me” molecular CD47 ligand) was overactivated in MRC1+TAMs and expressed on most of the tumor‐infiltrating macrophages, indicating that macrophages are important mediators of tumor immunosurveillance in the PCa microenvironment." (PMID 38483933, 2024).
tumor (continued). "Pathway analysis unveiled increased epithelial-mesenchymal transition in MRC1+ TAM, involved in extracellular matrix remodeling and promoting tumor metastasis." (PMID 39670859, 2025). "We believe this comprehensive approach will provide the necessary validation and insight into the interaction between MRC1+ TAMs and CXCL5+SLC6A14+ tumor cells." (PMID 39670859, 2025). "The most important markers of TAMs have been identified by studying tumours at different sites: CD163, CD204 (MSR1), CD206 (MRC1), MARCO, SIGLEC1 (CD169), stabilising protein-1 (Stab1) and Tie2 (TEK)." (PMID 39060648, 2024). "The M2 macrophages secrete anti-inflammatory molecules, including resistin-like-α, IL-10, Arginase-1, and mannose receptor C type 1 (MRC1), which help in resolution of inflammation and remodeling of injured lung tissue and tumor progression." (PMID 39120378, 2024). "The accumulation of MRC1+TIE2HiCXCR4Hi TAMs was accompanied by increased CXCL12 expression in vascularized, well-oxygenated areas after chemotherapy, which was important for tumor revascularization and relapse after chemotherapy." (PMID 39516356, 2024). "Lastly, mannose receptor C-type 1 (MRC1, also known as CD206), a marker for M2 macrophages, promotes tumor-supportive functions." (PMID 38786019, 2024). "Consistent with the scRNA-seq results, FOLR2 expression was also positively correlated with TRM-related genes (CD163, MRC1, CD163L1 and LYVE1) in the whole-tumor transcriptome from the TCGA STAD database." (PMID 39702278, 2024). "In constant, M2 macrophages express the surface markers of CD163, CD86, and CD206 (MRC1, mannose receptor C-type 1), secrete cytokines including IL-10, TGF-β, and IL-6, and function in wound repair and tumor growth." (PMID 37749600, 2023). "This plot showed that M2-like macrophage markers (MRC1 and CD163) had lower scaled intensities at tumour cell proximity than other macrophage markers." (PMID 37002343, 2023). "The macrophages in the invasive zone exhibited an M2-like phenotype with increased expression of CD163, MRC1, and SAAs receptor TLR2, whereas macrophages in the tumor tissue exhibited features of ECM remodeling and increased expression of MMP9 and MMP14." (PMID 37337030, 2023). "In the bulk tumor gene expression dataset (GSE64415), ZFTA-fused tumors had higher MRC1 expression than either PFA or PFB." (PMID 37694144, 2023). "SPP1+ macrophages expressed MRC1 (M2 marker), and TREM2 which correlates with tumor infiltrating CD8 exhaustion." (PMID 37633924, 2023). "The downregulation of Mrc1 (CD206) and Cd274 (PD-L1) was validated analyzing their protein expression on tumor-infiltrating live cells following Adoi treatment." (PMID 37553182, 2023). "We performed mIF staining of BrM tumor sections with CD3, CD14, CD206/MRC1, and α–smooth muscle actin (α-SMA), a major marker of brain blood vessels." (PMID 37655659, 2023). "On the other hand, the expression of many M2 signature genes—including those for FN1, MARCO, MRC1, MSR1, TGF-β1, and TGM2—decreased with tumor progression." (PMID 37441079, 2023). "Despite a greater proportion of M1 macrophages in the TME, M2 macrophages expressed higher gene level of CD163, MRC1 (CD206), TGF-β, IL10, VEGFA, and MMP9, which exhibited stronger tumor-promoting ability." (PMID 35033156, 2022). "Ligand-receptor interaction analyses indicated extensive cross-talk between the metastatic tumor cells and the MRC1+/CCL18+ macrophages; an example is the “don’t-eat-me” signaling between CD47 on tumor cells and SIRPA on the macrophages." (PMID 36376874, 2022). "Compared with several other tumor types, we found an inverse relationship between MKNK2 and the M2 markers CD163 and MRC1 (CD206) in human PDAC tumors." (PMID 35380995, 2022).
tumor (continued). "Further macrophage subsets were identified based on their high expression of CD68, CD163, and MRC1 (encoding CD206), which could be denoted as resident tissue macrophages and segregated into normal colon epithelial tissue (NLRP3+ and phospholipid transfer protein PLTP+) or tumor tissue (IL1B+)." (PMID 34572013, 2021). "Consistently, RNAseq analysis of human cancers revealed a strong positive correlation between the expression of Treg markers (FOXP3, IL2RA) and myeloid cell markers (MRC1, CD14, and ITGAM) across several tumor types." (PMID 32782249, 2020). "Tumor-infiltrating macrophages have been classified as M1 (antitumor) or M2 (protumor) according to the co-expression of CD68, iNOS or MRC1/CD206, CD163, Arg1, and other markers in in vitro models." (PMID 32168749, 2020). "Along the transition from M1 to M2 state, macrophages acquired features that promote tumor invasion, metastasis, and immunosuppression with upregulated genes like MMP14, VEGFA, and MRC1." (PMID 33298893, 2020). "We then characterized the features of the macrophage infiltrate at the tumor and metastatic sites by analyzing expression of the M1 marker CD11c and the M2‐like marker CD206 (MRC1) in F4/80+ cells." (PMID 32885605, 2020). "TAMs usually present an upregulation of cell-surface scavenger receptors, such as the mannose receptor (MRC1/CD206), which contribute to tumor immunosuppression, angiogenesis and metastasis." (PMID 31275860, 2019). "To investigate the localization and function of M1/M2 macrophages in the spleens and tumors of HT29 and CT26 tumor-bearing mice, we stained spleen and tumor sections with M1 and M2 macrophage markers, CD80 and MRC1, respectively." (PMID 29690614, 2018). "In tumor of HT29 tumor-bearing mice, CD80-expressing-cells predominantly localized with tumor cells, and MRC1-expressing cells were also present at steady state." (PMID 29690614, 2018). "In the spleens of HT29 tumor-bearing mice, CD80-expressing cells were very few and MRC1-expressing cells were dominant at steady state." (PMID 29690614, 2018). "Increased expression of CC3 following depletion of MRC1+ microglia/macrophages was strongly correlated with GFP-positive tumor cells, indicating tumor cell apoptosis." (PMID 29164051, 2017). "For the mast cell marker CMA1 and the macrophage marker MRC1, mRNA-levels in the normal mucosa of CRC patients were elevated compared to both healthy and tumor tissue." (PMID 29176937, 2017). "In the tumor tissue, CMA1 mRNA was low throughout, while MRC1 mRNA levels showed high inter-individual variations." (PMID 29176937, 2017). "We confirmed that MAMPCs and MAMs in the metastatic lung expressed significantly higher levels of CD14, CD36, CD64 (Fcgr1), CD206 (Mrc1) and CCR5 proteins compared with circulating C-MOs in the tumor-bearing mice." (PMID 29387063, 2017). "This question becomes more relevant since a recent study showed that CLASPIN, the human homologue of Mrc1, is stabilised by the deubiquitinating enzyme USP20 during checkpoint activation and that USP20 suppresses xenograft tumor growth." (PMID 26201080, 2015). "In analogy to the findings in tumor free lymph nodes a significantly decreased CD11c/CD68 and a significantly increased CD163/CD11c and MRC1/CD11c ratio was detected in the L1 cases compared to the L0 cases." (PMID 25042135, 2014). "M2-like TAM have high levels of mannose receptor-1 (MRC1/CD206), arginase-1 (Arg1), IL-10 and chemokines CCL22 and CCL17, whereas anti-tumor M1-like TAM express high interferon (IFN)γ and IL-1α/β levels; TNFα marks both M1- and M2-polarized TAM." (PMID 24317954, 2013). "In addition, direct validation through in vitro or in vivo experiments is essential to establish the interaction between MRC1+ TAMs and CXCL5+SLC6A14+ tumor cells." (PMID 39670859, 2025).
tumor (continued). "Single-cell expression analysis revealed that KRT5 and FABP7 were highly enriched in tumor cells, UGT2B4 was predominantly expressed in epithelial cells, BIRC3 and KLRB1 were enriched in CD8+ T cells, while MRC1 and CD209 were highly expressed in monocytes/macrophages." (PMID 40612672, 2025). "MRC1 is a well‐known marker gene for M2 macrophages, while MS4A4A is thought to have a role in macrophage function and polarization, particularly in the expression of M2 macrophages that are known to promote tumor development in GBM." (PMID 38997808, 2024). "Interestingly, most CIDGS-related genes, such as XRCC6, ST13, PES1, EFHD2, APOL2, ACTR2, and CDCP1, were markedly upregulated in HNSCC tumor samples, whereas several other genes, such as MARCO, MRC1, and CD83, were upregulated in healthy samples." (PMID 38666027, 2024). "Compared to non-treated mouse tumours, macrophages in CT-treated tumours showed significant upregulation of phagocytosis genes such as Stab1, Mrc1, Mertk and downregulation of ECM and angiogenesis such as Mmp9 and Col1a1." (PMID 39578450, 2024). "The fact that REG does not reduce Nos2, a M1-TAM marker, in contrast to Mrc1, is an indicator of an increased M1:M2 ratio impeding tumor growth." (PMID 37013652, 2023). "We then found that metastatic LN exhibited higher expression of MRC1 than that in the tumor, so it was determined that high C1QA+MRC1high macrophages might be related to tumor metastasis." (PMID 36569924, 2022). "M2 TAMs navigate through the collagen-dense tumor matrix aided by a palette of collagen-interacting proteins such as matrix metalloprotease MMP-9, collagenases and the collagen-endocyting receptor CD206 (mannose receptor, CD206/MRC1)." (PMID 32069856, 2020). "Our study showed that MRC1 expression in the spleen and the tumor was repressed after LPS injection in the xenograft tumor model but did not change in the allograft tumor model." (PMID 29690614, 2018). "In tumor resection specimens, the pan-macrophage marker CD68 showed a significant positive correlation with the other investigated macrophage markers (CD11c, CD163 and MRC1)." (PMID 30115022, 2018). "Expression of Arginase-1 (Arg-1), Found in inflammatory zone-1 (Fizz-1), chitinase 3-like-3 (Ym- 1), mannose receptor (MRC1/CD206) and Macrophage galactose-type C-type lectins 2 (MGL-2) were increased in B16F10-ARF−/− tumor xenografts, confirming M2 polarization of macrophages." (PMID 27572316, 2016). "Tumor free (n = 37) and metastatic (n = 17) lymph nodes of T1 and T2 oscc patients were processed for immunohistochemistry to detect CD68, CD11c, CD163 and MRC1 positive cells." (PMID 25042135, 2014). "The tumor cells themselves also do not express one of the two key receptors involved in the cellular internalization of rhASM – MRC1 – which also likely contributes to the diminished capacity of rhASM to reach HCC tumors in vivo." (PMID 23724146, 2013). "Interestingly, NR3C1 was co-expressed with MRC1 and CD163 in M03 cells, suggesting that NR3C1 may play a role in inhibiting immune-mediated tumor cell killing." (PMID 40260248, 2025). "Within the tumor microenvironment, M2 cytokines, including IL-4, IL-13, and IL-10, are present, and TAMs in various cancer models exhibit an M2 activation profile characterized by increased expression of CD163, MRC-1, C-type lectins, IL-10, and Arg-1, as well as reduced production of IL-12." (PMID 40544275, 2025). "Moreover, our bioinformatic analyses in individuals with cancer demonstrate that CDA levels are highest in 11 different tumor types with immunosuppressive features (that is, high in P2RY6, MRC1 and MSR1 levels in macrophages and low in IFNG and PRF levels in CD8+ T cells)." (PMID 38844817, 2024).
tumor (continued). "RT-qPCR results indicated a significant upregulation in the expression of M2 macrophage markers (MRC1, CD163) within HCC-conditioned TAMs, while the expression levels of M1 markers (CD86, iNOS) remained unchanged, suggesting a skew towards M2 polarization in the tumor microenvironment." (PMID 38938448, 2024). "Additionally, in metastatic tumors, MRC1 + CCL18 + macrophages, SPP1 + macrophages, and neutrophils were found to have significantly enhanced expression, suggesting a correlation between macrophage phenotype and tumor stage." (PMID 39068459, 2024). "The heatmaps of marker expression on the reduced dimensions showed that CD68 is the classical biomarker that is highly expressed by a large majority of macrophages; however, CD5L and MRC1 are differentially distributed with specific expression in adjacent non-malignant or tumor tissue." (PMID 36902024, 2023). "Thus, targeting the metabolic aberrations in tumor morphogens (CAFs) to reprogram the metabolism in macrophages and modulating the expressions of ARG1, MRC1, and MAPK signaling might lead to the discovery of novel therapeutic strategies." (PMID 33198082, 2020). "Based on tumor purity, we ascertained that most cytokines are secreted by TAMs and M2 macrophages, and marker sets have significant correlations with CDH11 in STAD, with examples including CCL-2, TGFB1, CXCL12, and MPP2 of TAMs and IL-10, IL1R1, CD163, and MRC1 of M2 phenotype (P < 0.0001)." (PMID 32685527, 2020). "Preoperative diagnostic biopsies (n = 26), tumor resection specimens (n = 34), tumor-free lymph nodes (n = 28) and lymph node metastases (n = 10) of T1/T2 oscc patients were immunohistochemically analyzed for Gal3 and macrophage marker (CD68, CD11c, CD163 and MRC1) expression." (PMID 30115022, 2018). "Notably, very few CD80-expressing cells and numerous MRC1-expressing cells were observed in the CT26 tumor compared with the HT29 tumor, and the populations did not change following LPS exposure." (PMID 29690614, 2018). "In contrast, at the 24‐h time‐point, 75% of the MHCII labeled macrophages in the tumor were also positive for MRC1 immunolabeling, indicating that in this 24‐h time window, originally M1 macrophages positive for MHCII switched in situ to a M2 phenotype, expressing the MRC1 marker." (PMID 29038312, 2017). "In our study, 10q11.23 (PRKG1), 10q22.1 (CSTF2T), 10p12.33 (MRC1), and 10p12.1 (STAM) occurred in 37.5% of ChRCC and not in RO, indicating the potential of the two cytobands in differentiating the two tumours." (PMID 39684226, 2024). "Some M1 markers (IL1A, IL1B, CD86), M2 markers (CCL18, MRC1/CD206, CSF1R), and TAM markers (HLA-DR, IL1RN, CD163, ITGAM, SIGLEC1/CD169) were highly expressed on both tumor and non-tumor macrophages." (PMID 33918618, 2021). "In the spleens of CT26 tumor-bearing mice, CD80- and MRC1-expressing cells were present but they did not increase following exposure to LPS." (PMID 29690614, 2018). "Moreover, after adjustment for tumor purity, FUNDC1 in LIHC had no relation to M1 macrophages but negatively correlated with ARG1+ M2 macrophages, while FUNDC1 in LUSC negatively correlated with ROS+ M1 macrophages and MRC1+ M2 macrophages." (PMID 31998650, 2019).